ENSG00000287856 (novel protein)
Gene: Protein-coding gene on chromosome 1 (231,363,797 to 231,528,603, reverse strand). Ensembl gene ENSG00000287856.
Genetic constraint (gnomAD): Loss-of-function variants: 5 observed, 19.71 expected, observed/expected ratio (o/e) 0.25, 90% interval 0.13 to 0.53. Missense variants: 80 observed, 176.63 expected, observed/expected ratio (o/e) 0.45, 90% interval 0.38 to 0.55. Synonymous variants: 57 observed, 55.98 expected, observed/expected ratio (o/e) 1.02, 90% interval 0.82 to 1.27.